BCL2 (BCL2 apoptosis regulator)
Diseases named in the same sentence as BCL2 in open-access papers (continued):
Sharing a sentence is not in itself a finding about the gene and the disease.
breast carcinoma (continued). "Our study first showed the synergistic effects of a BCL2 inhibitor ABT-263 and SM/z-VAD.fmk LCL161 with the aim of identifying a reinforcing anti-cancer effect that can be utilized as novel targeted agents in YARS-positive breast cancer." (PMID 33239070, 2020). "Reducing expression of antiapoptotic regulators such as cIAP 1, Bcl-2, catalase,clusterin, HO-1, livin, XIAP, HSP27 and claspin was also demonstrated in human breast cancer line; the latter in support of mithochondrial apoptotic pathway using bromelain-based CHCT." (PMID 34466585, 2020). "It has been reported that LINC00461/miRNA-149-5p/LRIG2 existed in hepatocellular carcinoma, LINC00461/miRNA-15a/miRNA-16/Bcl-2 happened in multiple myeloma, LINC00461/miRNA-30a-5p/integrin β3 occurred in breast cancer, and LINC00461/miRNA-411-5p/TOP2A participated in glioma." (PMID 33817241, 2020). "Similarly, apoptotic modulation of MCF7 breast cancer cells was attributed to Crocus sativus extract (CSE) and its major constituent crocin through time-dependent decrease of Bcl-2, upregulation of BAX, dowregulation of caspase-8 and -9 and cleaved caspase-3." (PMID 32859058, 2020). "Therefore, intracellular targets for the anticancer action of MGE include Bcl-2, Bax, cytochrome c, caspase-3, and PARP in human breast cancer." (PMID 32774407, 2020). "In addition to other members, decreased BAX/BCL-2 ratio and elevated MCL-1 expression were reported to be closely related with PTX resistance in breast cancer." (PMID 32547883, 2020). "For example, PFT induced apoptosis in murine metastatic breast cancer (4 T1) cells and in myeloid leukemia cells via a hole-piercing mechanism, as well as in AGS human gastric cancer cells via decreasing the polarization of MMP and Bcl2 expression." (PMID 32345289, 2020). "Oxymatrine treatment showed proapoptotic effects in breast cancer MCF-7 cells, and these effects correlated with the upregulation of Bax transcription and protein expression and the downregulation of Bcl-2 transcription and protein expression in a time- and dose-dependent manner." (PMID 32382295, 2020). "In addition, a calcium phosphate with polyelthyleneglycol (PEG)-polyanion polymer has recently been used to promote the delivery of siRNAs targeting the anti-apoptotic genes BCL-2 and BCL-xL in human breast cancer cells (MCF-7)." (PMID 31064156, 2019). "In contrast to Mcl-1 upregulation upon treatment with VU661013, we did not see upregulation of Bcl-2 or Bcl-xL in ER+ breast cancer cells treated with the Mcl-1 inhibitor." (PMID 31595181, 2019). "We report here that mTOR-dependent MCL1 translation rapidly drives Mcl-1 upregulation in ER+ breast cancer cells treated with ABT-263, or with BH3 mimetics that target Bcl-2 alone (ABT-199) or Bcl-xL alone (A1155463), consistent with the well-established oncogenic role of mTOR in ER+ breast cancers." (PMID 31595181, 2019). "In estrogen receptor positive breast cancer cells, resveratrol mediates apoptotic cell death via Bcl-2 downregulation that is independent of cytochrome c release and cleavage of caspases 3/8 and PARP." (PMID 31618928, 2019).
breast carcinoma (continued). "G0S2 was found epigenetically silenced in lung cancer and breast cancer lines, and engineered expression of G0S2 induced cell apoptosis through G0S2 binding to and antagonizing Bcl-2 in a lung and a colon cancer cell line but not in breast cancer cell lines." (PMID 30953555, 2019). "The reduced expression levels of anti-apoptotic proteins, Bcl2 and Stat3, plus cell cycle regulator protein, Cyclin D1, using Real-Time PCR confirm that the C-PC-induced death of MCF-7 human breast cancer cells occurred through the mitochondrial pathway of apoptosis." (PMID 31263160, 2019). "Furthermore, the expression level of Bax was significantly increased and the Bcl-2 level was decreased in 231/PTX cells treated with PTX plus UA compared with the levels in cells treated with PTX only.These results suggest that UA could reverse PTX resistance in breast cancer cells." (PMID 31259152, 2019). "TMP and the prescriptions can also reverse multidrug resistance induced by Dox in breast cancer, bladder cancer, hepatocellular carcinoma through regulating the expression and function of P-gp, MRP2, MRP3, MRP5, MRP1, GST, Bcl-2, and TOPO-II, or directly enhance the anti-cancer effect of Dox." (PMID 31885804, 2019). "In breast cancer, UBE2C knockdown increased the sensitivity of cancer cells to epirubicin and docetaxel and promoted the apoptosis induced by these two drugs through impaired the increased BCL-2 and MDR-1 expression levels." (PMID 30914455, 2019). "In contrast, n-3 PUFAs EPA and DHA have been shown to induce apoptosis via alteration of B-cell lymphoma 2 (Bcl-2) and procaspase-8 and reduce cell growth in both estrogen receptor-negative and positive breast cancer cells in vitro." (PMID 29342901, 2018). "Our data demonstrate that BCL2 and BCL(X)L inhibition profoundly impacts on mitochondrial ATP production, and that a combined treatment of BCL2 or BCL(X)L selective inhibitors and glycolysis inhibitors produced synthetic lethality in estrogen receptor positive (ER+) and TNBC breast cancer cells." (PMID 29899841, 2018). "It was shown in breast cancer cells that miR-125b-5p, miR-200c-3p, miR-409-3p, miR-122-5p, and miR-542-3p were modulated by RSV, thereby affecting antiapoptotic and cell cycle proteins such as Bcl-2 and CDKs." (PMID 29854071, 2018). "The aptamer-siRNA conjugates could be selectively taken by HER2-positive breast cancer cells and silence Bcl-2 expression, enhancing the sensitivity of HER2-positive breast cancer cells to chemotherapy." (PMID 29132385, 2017). "We show that the dissociation of Bcl-2 from Beclin 1 and subsequent enhancement of interaction among the ATG14-Beclin1-PI3KC3 complex lead to the induction of protective autophagy in TAM-resistant breast cancer cells." (PMID 28431397, 2017). "Our network analysis also allowed us to identify several specific proteins that EGCG may help regulate in breast cancer, including JUN, FADD, NFKB1, Bcl-2, GNAO1, and MMP14." (PMID 28713815, 2017). "In breast cancer, EI24 is a novel Bcl-2 binding protein which may contribute to apoptosis and low invasiveness by modulating the activity and/or function of Bcl-2." (PMID 28038450, 2017). "In this study, we first determined whether the change of interaction between Bcl-2 and Beclin 1 was responsible for the formation of protective autophagy in the established TAM-resistant breast cancer cells." (PMID 28431397, 2017).
breast carcinoma (continued). "In addition, BCL-2 is found to be an important downstream mediator of TFF3-stimulated anchorage-independent growth and anti-estrogen resistance in mammary carcinoma cells." (PMID 28445151, 2017). "The tumor sizes were significantly reduced in patients with HER2-positive, Tau-negative, Bcl-2-negative and high Ki67 index breast cancer." (PMID 29254147, 2017). "In addition, in breast cancer cells treated with BITC, the proapoptotic proteins Bax and Bak were upregulated and the antiapoptotic proteins Bcl-2 and Bcl-xL were downregulated, indicating that apoptosis was induced by BITC." (PMID 28698459, 2017). "AKT has recently been reported to be a critical regulator of CSC survival and maintenance of the CSC phenotype in breast cancer [75 Importantly, it was reported that the activation of the AKT and BCL-2 cell survival response in CSCs confer chemoresistance in HCC." (PMID 28445151, 2017). "Although there is no validated biomarker to predict resistance to taxanes in breast cancer, acquired resistance to paclitaxel in MCF-7 cells has been associated with BCL-2 upregulation." (PMID 29371916, 2017). "The BCL-2, MCL-1, and BCL-XL pro-survival proteins and the pro-apoptotic BH3-only ligand BIM are contemporaneously over-expressed in a significant proportion of the different breast cancer subtypes including the more aggressive basal-like." (PMID 29099748, 2017). "In addition, forced expression of NCOA3 observably enhanced Bcl-2 and phosphated AKT expression in the two breast cancer cells." (PMID 27831559, 2016). "Since lower concentrations of NO reduced proliferation of AA breast cancer cell lines, we further examined its effect on Mn SOD and Cu/Zn SOD as well as on various proliferation (cyclin D1 and PCNA), apoptosis (Bax and Bcl2), and oxidative stress (NOX4) markers." (PMID 27473585, 2016). "Interestingly, basal levels of Bcl2, an anti-apoptotic molecule was undetectable in HCC-1806, while its levels dramatically declined in MDA-MB-468 and MDA-MB-157 AA TN breast cancer cells with NO treatment." (PMID 27473585, 2016). "Although the Bcl-2/BAX ratio for induction of apoptosis showed the greatest decrease in response to 0.5 μg/ml of 5-FU, we selected the concentration of 1.0 μg/ml 5-FU following western blot analysis for co-treatment with human IFN-β in breast cancer cells." (PMID 26716512, 2016). "We performed flow cytometry to analyse cell cycle and apoptosis in ER-/Her2+ breast cancer cells, and then we analysed some markers of cell cycle and apoptosis by Western blotting, including PCNA, cyclin E, cleaved caspase-3, procaspase-3 and Bcl-2." (PMID 27494865, 2016). "More importantly, the ratio of Bax to Bcl-2, but not their absolute amount, is an important predictive index of the apoptosis of breast cancer cells." (PMID 27248325, 2016). "However, MYB knockdown greatly enhanced the sensitivity of breast cancer cells to several chemical agents, an effect mediated (at least in part) by the MYB target gene BCL2, since knockdown of the latter mimicked the sensitisation effects of MYB knockdown." (PMID 26812885, 2016). "Finally, we observed that APA exerts antiproliferative effects through inactivation of Akt and suppression of BCL-2 and MCL-1 in primary cancer cells from breast cancer patients." (PMID 26943775, 2016). "Previous studies have suggested that over-expression of miR-20a-5p may mediate breast cancer by targeting multiple cancer genes, such as PTEN and BCL2." (PMID 27329603, 2016).
breast carcinoma (continued). "Apoptosis plays important roles in the potential of quercetin to inhibit the proliferation of human MDA-MB-453 breast cancer cells that are mediated by up-regulation of BAX and down-regulation of Bcl-2 expression, as well as cleavage of caspase-3 and PARP proteins." (PMID 27657126, 2016). "Interestingly, a decline in anti-apoptotic Bcl2 and depolarization of MMP was observed in AA breast cancer cells." (PMID 27473585, 2016). "It seems that the anti-apoptotic effect of Bcl-2, which usually correlates with poor clinical outcome or resistance to therapy in tumors other than breast cancer, is evident only in cases without hormone receptors and without adjuvant therapy." (PMID 26472348, 2015). "The present findings also highlight Bcl-2 as a potential therapeutic target in breast cancers lacking conventional therapeutic targets such as triple-negative tumors." (PMID 26472348, 2015). "It has been reported that MYC and BCL2 act synergistically to promote primary cells into tumour cells, while in our work, MYC is dependent on BCL2 to influence the outcome of breast cancer (with p-value of 0.0119) and BCL2 also relies on MYC significantly (with p-value of 0.0388)." (PMID 24637666, 2014). "Our results showed that PTER-ITC activated PPARγ expression in a dose-dependent manner, followed by downregulation of its anti-apoptotic genes (Bcl-2 and survivin) to induce noteworthy levels of apoptosis in hormone-dependent (MCF-7) and -independent (MDA-MB-231) breast cancer cells." (PMID 25119466, 2014). "Moreover, the β2-M siRNAs inhibited Bcl-2 mRNA expression by inhibiting the phosphorylation of Akt and ERK in breast cancer cells with ER overexpression." (PMID 25292288, 2014). "As opposed to that, the involvement of caspase activation and Bcl-2 modulation was found not to be involved in gamma-tocotrienol-induced apoptosis in human breast cancer cells as discovered by Takahashi and Loo." (PMID 25480449, 2014). "Furthermore, previous studies have shown that Bcl-2 is a downstream target of ATF5 that mediates the pro-survival function of ATF5 in C6 glioma and MCF-7 breast cancer cells." (PMID 25120656, 2014). "In the present study, we observed that the expression of Bax and Puma was up-regulated, while the expression of Bcl-2 and Bcl-xL was significantly down-regulated in NNMT shRNA infected breast cancer cells, which resulted in the increase of the ratio of Bax/Bcl-2." (PMID 24558488, 2014). "PTEN expression in breast cancer cell lines has also shown to significantly inhibit the phosphorylation and DNA binding activity of NF-kB and transcription of its downstream targets which include VEGF and antiapoptotic genes Bcl-2 and Bcl-xL." (PMID 24416253, 2014). "The so-called proto-oncogene Bcl-2 is expressed in the normal mammary glandular tissues, as well as in the low- but not in the high-grade breast cancers." (PMID 23305095, 2013). "ACCA decreased Bcl-2 protein level (1.8-, 2.4-, and 2.6-fold, respectively) whereas Bax protein expression were elevated (3.4-, 2.4, and 3.2-fold, respectively) in MCF-7, T47D and MDA- 231 breast cancer cells, respectively." (PMID 24039831, 2013). "Increased of reactive oxygen species (ROS) production, coupled with downregulation of anti-apoptotic molecules (Bcl-2, Bcl-xL) led to reduction of mitochondrial membrane potential (MMP) and release of cytochrome c in both human breast cancer cells treated with vernodalin." (PMID 23437193, 2013).
breast carcinoma (continued). "Our systematic review of the literatures shows that negative Bcl-2 expression is a good prognostic factor for predicting sensitivity to chemotherapy of breast cancers." (PMID 24370277, 2013). "As shown in breast cancer, Gal-3 containing NWGR amino acid domain sequence as bcl-2 gene family also could act as antiapoptotic protein independently of Bcl-2, Bcl-XL, or Bax proteins." (PMID 24205440, 2013). "Indeed, increased BCL2 and XIAP protein contents were found in tumour spheroids of lung and breast cancer cells, respectively, in comparison to the corresponding monolayer cell cultures." (PMID 22797576, 2012). "On the basis of our data, we propose that combining γ-secretase inhibition with Bcl-2/Bcl-xL targeting, might allow us to use concentrations of GSI under the side-effect limit in breast cancer therapy." (PMID 22703841, 2012). "Bcl-2 expression or phosphorylation can also be up-regulated by VEGF in VEGFR+ primary and/or immortalized cancer cells from different sources, leukemia or in breast cancer." (PMID 22949815, 2012). "The SNP rs2279115 has been associated with BCL2 expression in CLL and breast cancer from node negative patients." (PMID 23961365, 2012). "These genes have significantly correlated expression with either ESR1 or BCL2 in the ER+ breast cancer subtype compared with other subtypes, but without differential expression." (PMID 22343619, 2012). "Pre-treatment with the inhibitor MG132 followed by CHX exposure resulted in no significant change in the Mcl-1 or Bcl-2 levels in the breast cancer cell lines MDA-MB-231, MDA-MB-468 and MCF-7 (data not shown)." (PMID 21730980, 2011). "Immunoprecipitation analysis confirmed that the decline in Mcl-1 and Bcl-2 (data not shown) was only in CHX-treated normal mammary epithelial cells but not in the CHX-treated breast cancer cells." (PMID 21730980, 2011). "In summary, the obtained results showed that D-glucuronyl C5-epimerase significantly suppress proliferative activity of breast cancer cells in vitro through the activation of tumour suppressor genes р53, BRCA1, SYK and E2F1 and change of a balance of pro- and apoptotic factors BCL2, NFKB1 and TNF." (PMID 20723247, 2010). "In our study, immunohistochemistry was used to detect the expression of BCL-2 and BAD in breast carcinoma, in addition, to analyze the relationship between the expression of the two genes and the expression of ER, PR histologic grade, clinical stage and the lymph node metastasis." (PMID 20691103, 2010). "In the case of breast cancer, a few studies have shown that IP3R could be the target of a variety of proteins such as Bcl-2 and cyclins that might affect cell viability by respectively suppressing apoptosis and probably stimulating proliferation." (PMID 20565939, 2010). "In this study we found that the sensitivity of the breast cancer cells to the 4 drugs were higher in the BCL-2 expression negative ones." (PMID 20691103, 2010). "The hypothesis is also supported by an increased expression of the anti-apoptotic genes BCL2, TNF and transcriptional factor NF-kappaB which protects breast cancer cells from apoptosis." (PMID 20723247, 2010). "It is reported that breast cancer cells overexpressing IKKε showed increased expression of Bcl-2 compared with cells without IKKε overexpression." (PMID 20863366, 2010). "Indeed we have shown here that BCL2, a known MYB target gene in other cell types, is directly regulated by MYB in breast cancer cells, and have identified multiple MBS within the BCL2 gene." (PMID 20659323, 2010). "The expression of BCL-2 and BAD can be used as prognosis factors of breast cancer." (PMID 20691103, 2010).